MIR877 (microRNA 877)
Synonyms: hsa-mir-877; MIRN877; miRNA877; mir-877
Gene: MicroRNA gene on chromosome 6 (30,584,332 to 30,584,417, forward strand). Ensembl gene ENSG00000216101.
Gene Ontology:
Biological process: miRNA-mediated post-transcriptional gene silencing
Cellular component: RISC complex
Homologues: Orthologues: chimpanzee ptr-mir-877 (99% identical), macaque mml-mir-877 (97% identical), rat Mir877 (84% identical), mouse Mir877 (83% identical).